RN7SKP187 (RN7SK pseudogene 187)
Gene: Miscellaneous RNA gene on chromosome 7 (112,288,623 to 112,288,952, forward strand). Ensembl gene ENSG00000202406.
Homologues: Orthologues: chimpanzee 7SK (98% identical). Paralogues in human: 7SK (88% identical), RN7SKP118 (85% identical), RN7SKP48 (83% identical), RN7SKP174 (82% identical), RN7SKP178 (82% identical), RN7SKP227 (81% identical), RN7SKP292 (80% identical), RN7SKP55 (80% identical), RN7SKP76 (79% identical), RN7SKP185 (79% identical), RN7SKP62 (79% identical), RN7SKP81 (76% identical), and 284 more.